HNF1B (HNF1 homeobox B)
Diseases named in the same sentence as HNF1B in open-access papers (continued):
Sharing a sentence is not in itself a finding about the gene and the disease.
tumor (continued). "When evaluating the immunohistochemical expression of HNF1B in our sample sets, there were significant differences among some of the four studied tumour types." (PMID 33051485, 2020). "Here, our data show that HNF1B directly represses SLUG in mediating its tumor suppressive role and establish a molecular link between EZH2 and EMT process." (PMID 31636385, 2020). "Both normal and tumor human-derived pancreatic organoids expressed lineage markers of the pancreas including HNF-1β, CK19 and SOX9." (PMID 33348809, 2020). "For instance, inhibition of circ-TTBK2, functioned as miR-217 sponge, was found to restrain tumor proliferation via down regulating HNF1β and Derlin-1." (PMID 31895689, 2019). "HNF1B and MSMB also encode multiple isoforms, and differential isoform expression for these genes has been observed in comparisons of tumor and normal prostate tissues." (PMID 29156765, 2017). "The tumour size of the nude mice injected with HNF-1β overexpression HCC cells was significantly larger than that of the control group." (PMID 28684878, 2017). "CA 125, CA 19–9, HNF-1β, and Annexin IV were demonstrated immunohistochemically in cancer cells from the original tumor and heterotransplanted tumors." (PMID 27259990, 2016). "This tumor-suppressor activity is lost when HNF1B is silenced by promoter methylation in the progression to PC." (PMID 27732966, 2016). "We found a significant correlation between rs11649743-G and elevated HNF1B levels in tumor tissue (n = 66) (p = 0.038), corresponding to the identification of the G-allele as the risk allele for PC." (PMID 27732966, 2016). "There is considerable evidence to indicate that HNF1B is over-expressed and behaves like an oncogene in clear cell OC, but is lost and acts as a tumor suppressor in HGS OC." (PMID 27732966, 2016). "Differential HNF1B isoform usage has been suggested to occur between benign and tumor prostate tissue." (PMID 25378557, 2015). "Many genetic and epigenetic alterations of HNF1β gene as well as several genetic networks and signaling pathways that are considered to be involved in the development and progression of tumor." (PMID 26464794, 2015). "The Spearman’s correlation analysis found that the expression of HNF-1B in hepatocytes of non-tumor tissue had a positive correlation with PI-DR (r = 0.312, P < 0.001)." (PMID 26311117, 2015). "Double immunostaining showed coexpression of HNF-1B and K7 in the ductular reaction cells of non-tumor tissue." (PMID 26311117, 2015). "In this review, we discuss some of the current developments about HNF1β and tumor, the relationship between HNF1β and stem/progenitor cells, and the potential pathogenesis of HNF1β in various tumors." (PMID 26464794, 2015). "Although many studies have investigated HNF1B in gynecological malignancies, such as CCC, showing its relationship with tumor cell survival and tumor-associated thrombosis, few data are reported on its role in EC." (PMID 25885815, 2015). "Higher tumor HNF-1B expression (HR: 1.443, 95% CI: 1.021–2.039, P = 0.038), higher TNM stage (HR: 1.802, 95% CI: 1.057–3.072, P = 0.030), and lymphovascular invasion (HR: 1.460, 95% CI: 1.057–2.017, P = 0.022) were independent predictors for DFS." (PMID 26311117, 2015). "In our data, HNF-1B expression in hepatocytes of non-tumor tissue was positively correlated with PI-DR, and was also significantly associated with DFS." (PMID 26311117, 2015). "Next, we analyzed the HNF-1B expression in surrounding non-tumor tissues(>2 cm away from tumor) of the HCC patients." (PMID 26311117, 2015). "HNF1B expression is altered in numerous cancers, with evidence to support a role as a tumor suppressor or oncogene depending on the tissue context." (PMID 25378557, 2015). "Restoration of HNF1β expression induced expression of HNF4α, a transcriptional target of HNF1β, indicating that epigenetic silencing of HNF1β leads to alteration of the hepatocyte nuclear factor network in tumours." (PMID 26464794, 2015).
tumor (continued). "HNF-1B expression in non-tumor tissues positively correlates with proliferative state of ductular reaction (PI-DR) in HCC patients." (PMID 26311117, 2015). "The following factors had a significant impact on DFS: higher tumor HNF-1B expression (P = 0.021), higher TNM stage (P = 0.004), larger tumor size (P = 0.033), and lymphovascular invasion (P = 0.020)." (PMID 26311117, 2015). "Here, by IHC and integrative computational analysis, we identify HNF1B as a marker of cytoplasmic clearing across diverse tumor types, supporting a likely direct role in glycogen accumulation." (PMID 24040285, 2013). "As such, HNF1B not only contributes to tumor cell survival, but elicits pleiotropic phenotypes of clinical significance." (PMID 24040285, 2013). "Restoration of TCF2 expression induced expression of HNF4α, a transcriptional target of HNF1β, indicating that epigenetic silencing of TCF2 leads to alteration of the hepatocyte nuclear factor network in tumours." (PMID 16479257, 2006). "However, immunostaining of two OCCC markers Napsin A and HNF1β showed to be discordant in the patient tumor." (PMID 37803448, 2023). "Cluster 1 was characterized by upregulation of tumor-suppressing genes: HNF1B, CCNDBP1, PATJ, EPB41L3, MARVELD2, PTEN in conjunction with cell-cycle genes – GSPT1, GPR19, EAPP, KIT, CDKL1, and stem cell markers – RBBP5, NANOG, NCSTN, ERG, including quiescent stem cell markers—FOXP1, SMARCA2." (PMID 36348001, 2022). "Epigenetic silencing of the HNF1B gene was observed in the cell lines due to methylation, decreasing the expression of HNF4α suggesting the role of hepatocyte nuclear factor network of genes in tumours." (PMID 33580750, 2021). "Comparison between unpaired and paired tumor and adjacent normal tissues from the KIRC cohort revealed that the expression of PAX8 and HNF1B was downregulated in tumor tissues, which might be different from some ccRCC cell lines." (PMID 33850477, 2021). "To further pin down the role of SLUG in HNF1B-mediated tumor suppressive function, we reintroduced SLUG to examine whether the tumorigenic ability could be restored in HNF1B overexpressed cells." (PMID 31636385, 2020). "Collectively, these results indicate the tumor suppressive role of miR-375-3p in LSCC via HNF1β, suggesting that miR-375-3p may serve as a potential target in the treatment of LSCC." (PMID 32863913, 2020). "Besides NKX2-1, we identified that HNF1B, a previously reported tumor suppressor found in other cancer types, STAT6, and SP100 were inactivated and linked to many silenced enhancers in a subgroup of LUAD." (PMID 32925947, 2020). "The authors hypothesize that the inactivation of HNF1B expression results in the deregulation of the transcriptional network, which leads to tumorigenesis and tumour progression." (PMID 33051485, 2020). "Depending on the type of the tumour HNF1B may act as a tumour suppressor or oncogene, although the exact mechanism by which HNF1B participates in the process of cancerogenesis is unknown." (PMID 33051485, 2020). "Therefore, the aim of our study was to precisely describe the spectrum of HNF1B ASVs in different types of tumour and corresponding healthy tissues." (PMID 32332782, 2020). "The major pathogenesis of sporadic ChRCC is HNF1β inactivation by transcriptional inactivation and post-transcriptional regulation as with tumor-suppressor genes, not by genomic mutations or promotor hypermethylation as in colorectal and ovarian CCRCC." (PMID 32150988, 2020). "The results of recent studies suggest that HNF1B may act as either a tumour suppressor or an oncogene, depending on the type of tissue and tumour." (PMID 32332782, 2020). "The different HNF1B expression suggests that in the setting of chRCC and ccRCC, HNF1B may be involved as a tumour suppressor, while in papRCC its role may be as a protooncogene." (PMID 33051485, 2020).
tumor (continued). "Nonetheless, the precise mechanism by which HNF1B participates in the process of cancerogenesis is unknown, and probably differs in different types of tumours." (PMID 33051485, 2020). "One of the possible explanations for this ambivalent function of HNF1B could be a tumour-specific expression of HNF1B ASVs, or a dysregulation in the splicing pattern resulting in the expression of divergent protein isoforms." (PMID 32332782, 2020). "Together, these findings demonstrated that risk-associated variation in HNF1B alters promoter methylation for HGSOC and CCOC in opposing directions, suggesting it may have a tumor suppressor role in HGSOC and a reverse, oncogenic role in CCOC." (PMID 33396385, 2020). "HNF1B is a transcription factor with tumor suppressive function, and our data indicate that it might be suppressed by the EZH2-mediated histone H3K27me3 pathway, in addition to previously reported DNA methylation." (PMID 31636385, 2020). "However, the original tumor of HOV5T was also positive for HNF1B suggesting the recapitulation of HOV lines with the original tumor." (PMID 31248002, 2019). "Similarly, both the xenograft and original tumor tissue of HOV5T expressed HNF1B though typical EM type tumors don’t." (PMID 31248002, 2019). "Patients with HCCs who were positive for both H3K36me3 and HNF1β had the highest incidence of high serum AFP level and high-grade tumor (P = 0.0061 and P = 0.0384, respectively) as well as borderline association with high-stage tumor (P = 0.0715)." (PMID 30356299, 2018). "In addition, IHC showed that the expression of HPC markers (CK7, CK19, SOX9 and CD133) was higher in the tumour formed by HNF-1β overexpression HCC cells than the control group." (PMID 28684878, 2017). "However, recent studies have shown that there is a clear correlation between HNF-1β and the occurrence and development of tumours." (PMID 28684878, 2017). "Multivariate analysis showed that higher tumour HNF-1β expression (hazard ratio (HR): 2.406, 95% CI: 1.415, 4.092, P = 0.007), higher TNM stage (HR: 3.596, 95% CI: 1.388, 9.314), and higher Edmondson grade (HR: 1.776, 95% CI: 1.086, 2.907) were independent predictors of DFS." (PMID 28684878, 2017). "MiR-217 exerted tumor-suppressive function through downregulating HNF1β." (PMID 28219405, 2017). "Low expression of HNF1B in some PDAC samples could reflect the tumor origination from acinar cells with incomplete ductal reprogramming phenotype (as suggested by one of our peer reviewer)." (PMID 27520560, 2016). "Taken together, these observations suggest that HNF1A and HNF1B can be co-expressed in normal pancreatic tissues and may act as tumor suppressors through their regulatory activity." (PMID 27520560, 2016). "HNF1β is a prognostic factor and a potential tumor suppressor, and could be a potential therapeutic target for RCC." (PMID 26464794, 2015). "We investigated HNF-1B expression using immunohistochemistry (IHC) in the primary tumor tissue." (PMID 26311117, 2015). "Patients with high HNF-1B expression in non-tumor tissue were likely to be with poor DFS." (PMID 26311117, 2015). "The expression of HNF1β in tumor tissue could predict recurrence and HCC-specific death after transplantation." (PMID 26464794, 2015). "Studies found that HNF1β expression was reduced in tumor tissue compared with normal kidney tissue." (PMID 26464794, 2015). "Several studies suggest a role of HNF1β in tumor formation and various kinds of renal disease." (PMID 26464794, 2015). "These cases expressed HNF-1β in approximately 70% and 30% of tumor cells, respectively." (PMID 25884453, 2015). "Collectively then, the summarised findings suggest that impairment of the HNF1β/HNF4α signalling network may lead to tumour formation." (PMID 16479257, 2006).
tumor (continued). "Interestingly, HNF1B functions as a protooncogene in some tumors, while it acts as a tumor suppressor in others, and whether it behaves as an oncogene or tumor suppressor appears to depend on the type and histogenesis of the tumor." (PMID 39915461, 2025). "In the setting of chRCC, HNF1B may therefore have a tumour suppressive effect." (PMID 33051485, 2020). "Thus, decreased urinary levels of FXYD2 and UMOD derived peptides may indicate inhibition of HNF1B transcriptional activity by a mediator released at the tumor site into the circulation." (PMID 31900160, 2020). "As such, the role of HNF1B in ccRCC could therefore be in the form of a tumour suppressor." (PMID 33051485, 2020). "Thus, further study for HNF1β with tumor and stem cell is still needed." (PMID 26464794, 2015). "Immunohistochemistry revealed that the tumor cells were positive forcytokeratin AE1/AE3, hepatocyte nuclear factor-1-beta (HNF1β) and PAX8 andnegative for thyroglobulin and thyroid transcription factor-1 (TTF-1)." (PMID 39700333, 2024). "Consistent with their cholangiocellular features, all tumor cells were positive for the bile duct markers CK19 and CK7 and the cholangiocyte-specific transcription factor HNF1B." (PMID 35655220, 2022). "Immunohistochemically, the tumor cells showed expression of SALL4 (sal-like protein 4), HNF1B (hepatocyte nuclear factor 1-beta), PAX8 (paired box gene 8), and α-FP (alpha fetoprotein)." (PMID 35204394, 2022). "Hepatocyte nuclear factor 1b (HNF1b) is a known prognostic biomarker in many cancer types including PDAC, where it plays a role suppressing tumor progression." (PMID 34031415, 2021). "However, more data is needed to confirm that hypothesis, especially given that this result is in stark contrast to the other most common tumour with a clear cell phenotype, OCCC, because in OCCC the overexpression of HNF1B is a common phenomenon and has been linked to the development of this tumour." (PMID 33051485, 2020). "However, whether elevated HNF1B levels lead to tumour transformation and disease progression is not yet understood and functional studies to examine whether HNF1B variants influence cancer prognosis are lacking." (PMID 27437873, 2016). "Similarly, our data suggests that that HNF1B may act as a tumor suppressor in benign prostate tissue, where it works normally to suppress classic features of tumorigenesis, by stimulating transcription of genes with clear roles in controlling cellular proliferation, adhesion and movement." (PMID 27732966, 2016). "Kaplan-Meier survival analysis showed that the median (95% CI) DFS time was 15.33 (13.34–17.33) and 11.97 (10.48–13.45) months respectively for patients with low HNF-1B expression and high HNF-1B expression in non-tumor tissue (P = 0.014)." (PMID 26311117, 2015). "Next, we further identify the correlation between HNF1B expression and HPC and biliary markers expression (IOD) in tumor tissues." (PMID 26311117, 2015). "Upregulation of HNF1 homeobox B (HNF1B/HNF-1β) in OCCC cells can induce the expression of nuclear factor kappa B (NF-κB), which then induces the expression of PD-1 and its ligand PD-L1, facilitating the immune escape of tumor cells." (PMID 40658469, 2025). "The mechanism might be related to the fact that HNF-1β can protect cancer cells by regulating the glucose metabolism of OCCC cells and reducing ROS in the tumor microenvironment." (PMID 38347608, 2024). "However, the tumor’s histology completely matched that of ovarian CCA, and the tumor cells expressed specific markers CK7, PAX-8, NapsinA, and HNF-1β, consistent with the immunophenotype of female genital tract ovarian CCA." (PMID 39533590, 2024).
tumor (continued). "Other copy number reduced genes included SMAD4, HNF1B, and some gene loci that are not known to be tumor suppressor genes, such as KRAS, MYC, PIK3CA, and IL6." (PMID 36430324, 2022). "We described the spectrum of HNF1B ASVs in non-malignant tissues and the quantitative changes of the HNF1B ASVs in corresponding tumours." (PMID 34997048, 2022). "We conclude that expression of a single biomarker (e.g., HNF1β and GATA3) should not be interpreted as diagnostic of a particular tumor type without taking into consideration the histology." (PMID 33986807, 2021). "For example, our result confirmed previous findings that rs4430796 is an eQTL for HNF1B only in the tumor-adjacent benign samples, but not in tumor samples." (PMID 32226005, 2020). "When any tumor demonstrates a CK7 patch positive/c-kit positive/ HNF-1β totally negative result, this favors ChRCC over RO." (PMID 32150988, 2020). "As we identified HNF1B to be the strongest master regulator (NES = 5.036), we studied the expression of HNF1β on the protein level using immunohistochemistry (IHC) staining in normal and PDAC tumor samples." (PMID 27520560, 2016). "In vitro functional assays together with gene expression data from matched cancer and non-cancer patient tissue suggest that HNF1B exerts a tumor-suppressive effect when over-expressed in cancer cells." (PMID 27732966, 2016). "Seromucinous tumor cells were positive for estrogen receptor (ER) and progesterone receptor (PgR) but negative for Napsin A, p504S, and HNF1B." (PMID 26075120, 2015). "Moreover, restoration of TCF2 expression induced expression of HNF4α, a transcriptional target of HNF1β, indicating that epigenetic silencing of TCF2 leads to alteration of the hepatocyte nuclear factor network in tumours." (PMID 16479257, 2006). "The tumor cells were positive for HNF1-β and PAX-8, but negative for WT-1 and ER." (PMID 41479789, 2025). "Hence, we believe that HNF-1β inhibitors may be a future therapeutic strategy to improve the prognosis of OCCC patients, and the energy metabolism of tumor cells might direct us to future OCCC targeting research." (PMID 38347608, 2024). "Therefore, changes in the HNF1B splicing pattern are probably not the key mechanism in the regulation of gene expression of fully functional HNF1B protein in the analysed tumour tissues." (PMID 34997048, 2022). "Therefore, HNF1B ASVs 3p, Δ7, Δ7–8, Δ5–8, and Δ6–8 ASVs were chosen for subsequent precise quantitative characterization in a wide spectrum of tumour (T) and non-tumour (NT) samples in a number of tissues presented in this work." (PMID 34997048, 2022). "Observed changes in the HNF1B splicing pattern may be a consequence of the overall tumour splicing disbalance rather than presence of potential deep intronic variants with splicing effect." (PMID 34997048, 2022). "FLRT3 is most strongly co-expressed with tumor suppressor gene TP63 and angiogenesis regulator gene NTN4 (Pearson correlation r = 0.83) (CBioportal), which suggests possible mechanisms by which HNF1B could exert the effects observed here – a control switch preventing EMT in non-tumor tissue." (PMID 27732966, 2016). "The regulatory mechanisms and pathways in which HNF1B is involved in the process of carcinogenesis are not clear, but it appears that HNF1B may act as either oncogene or oncosuppressor gene based on the type of tumor and its histogenesis." (PMID 32873863, 2020).